JAML (junction adhesion molecule like)
Description:
Transmembrane protein of the plasma membrane of leukocytes that control their migration and activation through interaction with CXADR, a plasma membrane receptor found on adjacent epithelial and endothelial cells. The interaction between both receptors mediates the activation of gamma-delta T-cells, a subpopulation of T-cells residing in epithelia and involved in tissue homeostasis and repair. Upon epithelial CXADR-binding, JAML induces downstream cell signaling events in gamma-delta T-cells through PI3-kinase and MAP kinases. It results in proliferation and production of cytokines and growth factors by T-cells that in turn stimulate epithelial tissues repair. It also controls the transmigration of leukocytes within epithelial and endothelial tissues through adhesive interactions with epithelial and endothelial CXADR.
Synonyms: AMICA1; Gm638; AMICA; CREA7-1; CREA7-4
Tractability: Antibody: UniProt places it where antibodies can reach, with high confidence; its Gene Ontology location is reachable by antibodies, with high confidence; UniProt predicts a signal peptide or a membrane-spanning region; the Human Protein Atlas places it where antibodies can reach.
Gene: Protein-coding gene on chromosome 11 (118,193,725 to 118,226,323, reverse strand). Ensembl gene ENSG00000160593.
Subcellular location: Cell membrane; Cell junction
Subcellular location (Human Protein Atlas): Plasma membrane; Nucleoplasm
Pathways (Reactome):
Hemostasis: Cell surface interactions at the vascular wall
Immune System: Immunoregulatory interactions between a Lymphoid and a non-Lymphoid cell
Gene Ontology:
Molecular function: cell adhesion molecule binding; integrin binding; protein binding; protein homodimerization activity
Biological process: heterophilic cell-cell adhesion; monocyte extravasation; neutrophil chemotaxis; neutrophil extravasation; gamma-delta T cell activation; positive regulation of epithelial cell proliferation involved in wound healing; immune system process
Cellular component: anchoring junction; bicellular tight junction; plasma membrane; membrane
Genetic constraint (gnomAD): Loss-of-function variants: 22 observed, 37.56 expected, observed/expected ratio (o/e) 0.59, 90% interval 0.42 to 0.84. The upper end of that interval is the gene's LOEUF score, 0.84, which puts it in group 3 of 6, group 1 being the genes least tolerant of losing a copy. Missense variants: 416 observed, 486.45 expected, observed/expected ratio (o/e) 0.86, 90% interval 0.79 to 0.93. Synonymous variants: 155 observed, 180.69 expected, observed/expected ratio (o/e) 0.86, 90% interval 0.75 to 0.98.
Homologues: Orthologues: chimpanzee JAML (99% identical), macaque JAML (91% identical), dog JAML (69% identical), pig JAML (67% identical). Paralogues in human: MPZL1 (14% identical), SCN2B (13% identical), MPZL2 (13% identical), SCN4B (13% identical), MPZ (11% identical), MPZL3 (11% identical).
Diseases named in the same sentence as JAML in open-access papers:
JAML is named in the same sentence as 41 diseases in open-access papers, as found by Europe PMC text mining. Sharing a sentence is not in itself a finding about the gene and the disease. The quoted sentences say what the papers report.
gastric cancer (6 papers, 2021 to 2025). A primary or metastatic malignant neoplasm involving the stomach. "Fn1 and JamL serve as prognostic biomarkers for breast and thyroid cancers, lung adenocarcinoma, and gastric cancer, while Ddit4 is a potential prognostic biomarker for colorectal cancer 27-32." (PMID 40206211, 2025). "Gastric cancer cells overexpressing JAML exhibited enhanced migratory and proliferative abilities via activation of the p38 signaling pathway." (PMID 40636111, 2025). "In gastric cancer, overexpressed JAML facilitated the proliferation and migration of gastric cancer cells." (PMID 35672776, 2022). "Junctional adhesion molecule-like protein (JAML), is recognized as a tumorigenesis molecule in gastric cancer." (PMID 35672776, 2022). "The expression of JAML was examined in gastric cancer (GC) and peritumoral tissues from 63 patients." (PMID 33777731, 2021). "Previous studies have shown that JAML promotes tumor progression in gastric cancer in vitro." (PMID 35672776, 2022). "JAML promoted gastric cancer (GC) cell migration and proliferation partially via p38 signaling." (PMID 35356274, 2022).
acute kidney injury (5 papers, 2022 to 2025). Sudden and sustained deterioration of the kidney function characterized by decreased glomerular filtration rate, increased serum creatinine or oliguria. "Further significantly upregulated transcripts related to inflammatory processes included ADAM19, PD-L1 (CD274), non-canonical NF-kB genes NFKB2 and RELB, furthermore IFITM1, JAML -linked with acute kidney injury - IRX3-linked with metabolic inflammation - and PRDM1-observed in gouty arthritis." (PMID 40281125, 2025). "At the same time, JAML regulates macrophage polarization and lipid metabolism in renal podocytes, influencing the onset and progression of acute kidney injury and diabetic nephropathy." (PMID 40636111, 2025). "Heterotrimeric G proteins are required for the Kidney Injury Molecule-1 (KIM-1)-mediated clearance of renal tubular epithelial cells in an acute kidney injury (AKI) model, as is the junctional adhesion molecule-like protein (JAML), which mediates macrophage polarisation for injury resolution." (PMID 38473905, 2024).
diabetic kidney disease (4 papers, 2021 to 2025). Progressive kidney disorder caused by vascular damage to the glomerular capillaries, in patients with diabetes mellitus. "Our team has revealed for the first time that the WYJDTLF can improve lipid metabolism abnormalities in db/db mice and alleviate diabetic kidney disease-induced renal pathological damage by inhibiting the JAML/SIRT1 signalling pathway." (PMID 40837398, 2025). "Podocyte specific deletion of JAML alleviates pathologies related to diabetic kidney disease such as lowering renal lipotoxicity impairing the progress of the disease." (PMID 34319011, 2021). "In addition to our recent finding that JAML mediates podocyte lipid metabolism in diabetic kidney disease, we further found that JAML regulated macrophage phenotype polarization in this study." (PMID 35708906, 2022).
mammary tumor (3 papers, 2021 to 2023). "Phenotypic analysis of the markers we identified by scRNAseq revealed that expression of CXCR6, ICOS, JAML, NK1.1, NKG2D, and PD-1 by Vγ4+ and Vγ6+ cells remains unaffected by mammary tumor conditioning." (PMID 36480166, 2023).
myeloid leukemia (3 papers, 2021 to 2023). A clonal proliferation of myeloid cells and their precursors in the bone marrow, peripheral blood, and spleen. "It has been found that JAML can promote the adhesion of leukocytes to endothelial cells in myeloid leukemia." (PMID 33777731, 2021).
acute promyelocytic leukemia (2 papers, 2022 to 2025). An aggressive form of acute myeloid leukemia (AML), characterized by arrest of leukocyte differentiation at the promyelocyte stage, due to a specific chromosomal translocation t(15;17) in myeloid cells. "Studies have shown that JAML is expressed in neutrophils, monocytes, tissue-resident γδT cells, activated lymphoid γδT cells, αβT cells, and acute promyelocytic leukemia cells." (PMID 40636111, 2025).
acute tubular necrosis (2 papers, 2022 to 2025). "By immunohistochemical (IHC) staining analysis, we first observed the upregulation of JAML in kidneys from patients with biopsy-proven acute tubular necrosis (ATN), which is one of the most common causes of AKI." (PMID 35708906, 2022). "Immunohistochemical analysis revealed prominent JAML expression in renal tubular epithelial cells and macrophages within the tubular interstitium of patients diagnosed with acute tubular necrosis (ATN)." (PMID 40837398, 2025).
atherosclerosis (2 papers, 2021 to 2025). A disease characterized by the build-up of fatty material and calcium deposition in the arterial wall resulting in partial or complete occlusion of the arterial lumen. "Although it has been found that JAML plays exact roles in the process of wound healing and atherosclerosis in recent years, its role in the tumor has been poorly investigated." (PMID 33777731, 2021). "The role of JAML in lipid metabolism may also extend to other diseases, including atherosclerosis, Alzheimer’s disease, Parkinson’s disease, cardiovascular diseases, and age-related macular degeneration." (PMID 40636111, 2025). "Our recent study found that JAML silencing delayed the formation of atherosclerosis in mice." (PMID 33777731, 2021).
colorectal cancer (2 papers, 2025). A primary or metastatic malignant neoplasm that affects the colon or rectum. "Evidence has shown that JAML is involved in this pathway, where it can promote the proliferation, migration, and invasion of colorectal cancer cells by activating the PI3K-AKT-mTOR signaling pathway." (PMID 40636111, 2025). "Yanan Liu and colleagues explored the prognostic significance of JAML in colorectal cancer (CRC) by analyzing tumor samples from 50 CRC patients." (PMID 40636111, 2025).
glomerular disease (2 papers, 2025). "This research established a critical connection between JAML and lipid metabolism, identifying JAML as a novel driver of glomerular disease progression through its role in podocyte lipid metabolism." (PMID 40636111, 2025). "Junctional adhesion molecule-like protein (JAML) is expressed in the podocyte in higher amounts in mice with proteinuria from glomerular disease." (PMID 39940317, 2025).
melanoma (2 papers, 2022 to 2023). A malignant, usually aggressive tumor composed of atypical, neoplastic melanocytes. "This suggests that CAR loss, observed during advanced stages of melanoma, may cause a reduction in JAML-CAR interaction-induced anti-tumour immunity mediated by CD8 and tumour-associated γδ." (PMID 37306404, 2023). "Mice lacking JAML protein expression (Jaml−/−) were more susceptible to both B16F10 melanoma tumor formation and growth, which was associated with decreased activity of γδ T cells." (PMID 35480230, 2022).
acute monocytic leukemia (1 paper, 2022). Acute monoblastic leukemia (AML-M5), is one of the most common subtypes of acute myeloid leukemia (AML) that is either comprised of more than 80% of monoblasts (AML-M5a) or 30-80% monoblasts with (pro)monocytic differentiation (AML-M5b). "In addition, knockdown of JAML in a human acute monocytic leukemia cell line, THP‐1, decreases adhesion and migration of monocytes." (PMID 35334492, 2022).
asthma (1 paper, 2021). "It is also well known as a co-ligand for junction adhesion molecule like (JAML), which is a cell signaling receptor of the immune system implicated in asthma, cancer, and chronic nonhealing wounds." (PMID 33802680, 2021). "Additionally, CAR is well known as a co-ligand for JAML protein, which is altered in the immune system with implications for asthma, cancer, and chronic nonhealing wounds." (PMID 33802680, 2021).
gastric tumors (1 paper, 2021). "To investigate the relationship between JAML and tumor development, we selected gastric tumors as the research object." (PMID 33777731, 2021).
ischemia reperfusion injury (1 paper, 2025). Adverse functional, metabolic, or structural changes in ischemic tissues resulting from the restoration of blood flow to the tissue (reperfusion), including swelling; hemorrhage; necrosis; and damage from free radicals. "Clinical studies have demonstrated a significant upregulation of JAML expression in renal tissues affected by ischemia-reperfusion injury (IRI), with this elevated state persisting for up to 72 h post-injury." (PMID 40837398, 2025).
lipid metabolic disorders (1 paper, 2025). "In recent years, JAML, the most recently discovered member of the JAM family, has gained increasing attention for its roles in lipid metabolism disorders, inflammatory responses, tumor cell proliferation and migration, and antitumor immunity." (PMID 40636111, 2025).
multiple sclerosis (1 paper, 2025). A progressive autoimmune disorder affecting the central nervous system resulting in demyelination. "Both secretory and constitutive forms of JAML can bind to its receptor CAR, thereby influencing the migration of T cells and neutrophils across various barriers in the body, which in turn affects the progression of inflammatory responses, multiple sclerosis, and other disease processes." (PMID 40636111, 2025).
relapsing-remitting multiple sclerosis (1 paper, 2025). The most common clinical variant of multiple sclerosis, characterized by recurrent acute exacerbations of neurologic dysfunction followed by partial or complete recovery. "During relapsing-remitting multiple sclerosis (RRMS), JAML is proposed to mediate CNS leukocyte migration through heterotypic interactions with CAR in the choroid epithelial cells of the blood-brain barrier." (PMID 40636111, 2025).
renal fibrosis (1 paper, 2025). A final common manifestation of a wide variety of chronic kidney diseases characterized by glomerulosclerosis and tubulointerstitial fibrosis. "Renal histopathological analyses reveal progressive exacerbation of renal fibrosis, lipid accumulation, inflammatory indicators, and JAML/Sirt1 signaling pathway abnormalities correlating with disease severity." (PMID 40837398, 2025).
steatosis (1 paper, 2024). Increased lipid within the cytoplasm of cells. "Therefore, we selected the RPS6KA1 and LMCD1 genes as diagnostic for steatosis and AS, and the RPS6KA1 SYNP02, JAML and SERPINA3 genes as diagnostic for NASH and AS." (PMID 38606153, 2024).
tumor (13 papers, 2018 to 2026). "Intriguingly, high tumor-derived JAML expression in CRC patients was associated with reduced infiltration of CD3+ and CD8+ T lymphocytes, an observation further validated in animal models." (PMID 40636111, 2025). "This undoubtedly hinders the clinical translation of JAML, so there is a need to develop tumor-specific JAML antibodies to minimize the risk of off-target effects." (PMID 40636111, 2025). "First, we found JAML was significantly upregulated in GC tissues by IHC and was associated with higher tumor malignancy." (PMID 33777731, 2021). "JAML-associated mechanisms in tumor promotion/inhibition and their clinical applications." (PMID 40636111, 2025). "We also explored the underlying mechanisms by which JAML affects tumor progression in LUAD." (PMID 35672776, 2022). "The result that high JAML levels were associated with higher tumor malignancy in GC patients encouraged us to assess whether JAML was related to oncogenic function." (PMID 33777731, 2021). "The elevated expression of JAML in tumor tissues has recently garnered significant attention, with studies revealing its role in enhancing tumor cell proliferation and migration, thereby contributing to increased malignancy." (PMID 40636111, 2025). "By focusing on JAML’s specific overexpression in tumor tissues, we assess its potential as a novel therapeutic target for cancer." (PMID 40636111, 2025). "Particular attention is given to the effects of JAML on tumor cell proliferation and migration, alongside its pivotal role in regulating lymphocyte infiltration into the tumor microenvironment." (PMID 40636111, 2025). "Given its dual roles in immune and tumor cells—exhibiting both antitumor and protumor effects—JAML’s therapeutic potential in cancer treatment warrants further investigation." (PMID 40636111, 2025). "When highly expressed in T lymphocytes, JAML enhances immune responses and exerts anti-tumor effects by boosting the tumor-killing capabilities of T lymphocytes within the tumor microenvironment (TME)." (PMID 40636111, 2025). "Collectively, The balance between JAML’s pro-inflammatory and anti-tumor functions underscores its therapeutic promise." (PMID 40636111, 2025). "Within tumor microenvironments, tumor-derived JAML promotes tumor cell proliferation and migration, facilitates malignant progression, and suppresses T lymphocyte infiltration by downregulating chemokine secretion." (PMID 40636111, 2025). "Animal studies suggest that combining agonistic anti-JAML antibodies with PD-1 inhibitors achieves enhanced tumor suppression compared to PD-1 monotherapy." (PMID 40636111, 2025). "There were two exceptions to this observation: the proportion and MFI of ICOS on Vγ4+ cells as well as MFI of JAML on Vγ6+ cells was increased in tumor-bearing KB1P mice." (PMID 36480166, 2023). "Our data show that Vγ6+ cells express a phenotype with high degree of similarity to Trm CD8+ T cells through production of CXCR6, ICOS, JAML, and PD-1, whose expression is stable between tumor-free and tumor-bearing mice." (PMID 36480166, 2023). "The results show that overexpression of JAML significantly increased the xenograft tumor volume and vice versa." (PMID 35672776, 2022). "During the early stages of tumor growth, Jaml−/− mice had fewer numbers of IFNγ-producing γδ tumor-infiltrating lymphocytes (TIL) demonstrating that the γδ T cell response to B16 tumor growth is mediated, at least in part, by JAML-CXADR interactions." (PMID 35480230, 2022). "Our results demonstrated that JAML expression was significantly elevated in tumor tissues when compared with peritumor tissues." (PMID 35672776, 2022). "IHC analysis confirmed the results that expression of JAML in tumor tissues was significantly upregulated in 30 pairs of LUAD tissues." (PMID 35672776, 2022). "To in-depth clarify the actual function of JAML in tumorigenesis in vivo, a subcutaneous xenograft tumor model in nude mice with LUAD cells was established." (PMID 35672776, 2022).